CRP (C-reactive protein)
Diseases named in the same sentence as CRP in open-access papers (continued):
Sharing a sentence is not in itself a finding about the gene and the disease.
depression (continued). "Furthermore, evidence shows that depression is related to inflammatory markers such as interleukin 1,6 and C-reactive protein, which could be used as independent prognostic variables of OC." (PMID 36556009, 2022). "Importantly, most of the community members who were caught in the WTC dust cloud on 9/11 also had a traumatic life-threatening experience, thus, we and others have reported that elevated levels of CRP were associated with symptoms of PTSD and depression among the members of the WTC EHC." (PMID 35886474, 2022). "CRP levels are not consistently associated with ACEs and depression in children and young people." (PMID 35241782, 2022). "The association of DII and depression was not explained by CRP." (PMID 35565951, 2022). "Furthermore, the upregulation and downregulation of IL6 and CRP affect depression severity." (PMID 36009493, 2022). "In addition, raising the level of inflammatory cytokines such as interleukein 6, C-reactive protein, and leptin resistance may also be involved with depression." (PMID 35458097, 2022). "The lack of difference in results of the analyses using inflammatory-related and non-inflammatory related smoking IVs, suggest that there is no clear distinct CRP mediated inflammatory causal pathway mediating the causal relationship detected between smoking and depression." (PMID 36057695, 2022). "Further studies are necessary to resolve this debate and determine what role, if any, is played by CRP in HIV-associated depression, as this understanding may aid in developing translational tools for subtype-specific screening of depression in people living with HIV." (PMID 35618889, 2022). "Furthermore, there is a lack of consistency in detection of the associations of CRP with reward-related corticostriatal function and psychiatric disorders (e.g., depression) in adolescents." (PMID 35873737, 2022). "The OR for ↑WS depression was 2.03 (1.62–2.55), 1.36 (1.10–1.68), 0.62 (0.49–0.79) and 1.30 (1.04–1.61) in the 10th PRS decile v. the 1st PRS decile for BMI, CRP, daily alcohol use and MDD, respectively." (PMID 32624019, 2022). "However, the sequential order between depression status and elevated CRP remains unclear and requires further research." (PMID 34943627, 2021). "The lack of association between depression symptoms and IL-6 or CRP in our cohort as compared to other cohorts may reflect differences in the distribution of age, sex, or body composition between the cohorts." (PMID 32691611, 2021). "We report that CRP is unlikely to be causally related to schizophrenia and depression." (PMID 34280516, 2021). "In addition, although observational studies have consistently reported elevated CRP and IL-6 levels in depression and schizophrenia, MR analysis has reported a protective effect of CRP for schizophrenia." (PMID 33684738, 2021). "A previous meta-analysis reported no sex-specificity of the association between CRP and depression." (PMID 34505025, 2021). "We have examined specificity and potential causality of associations for CRP and IL-6 with depressive and anxiety symptoms using large-scale data from two well-established European cohorts, UK Biobank (UKB) and Netherlands Study of Depression and Anxiety (NESDA)." (PMID 34135474, 2021). "However, either GE in MRI or CRP elevation were associated with BDI scores corresponding on average to a minimal or mild depression, while patients with both CRP elevation and GE in MRI had BDI scores which corresponded to at least a moderate depression." (PMID 34764926, 2021). "In a study that followed adolescent females at higher risk of depression for more than 2.5 years study, adolescents with a history of early life stress had greater increases in IL-6 and CRP when they became depressed than their peers without a history of early life stress." (PMID 34890365, 2021).
depression (continued). "Female sex was associated with current depression, both in groups with raised CRP (OR = 7.83; 95 % C.I., 1.78−34.40) and without (OR = 2.35; 95 % C.I., 1.64−3.35), but the association was stronger for cases with raised CRP (Holm-corrected p-value for likelihood ratio test <0.001)." (PMID 32339985, 2020). "There were no longitudinal associations between DGIH/BMI and depression, and adjustment for IL-6 and C-reactive protein did not attenuate associations between IR/BMI and depression; however, the longitudinal analyses may have been underpowered." (PMID 30854996, 2020). "We report that the proportion of patients with depression showing elevated inflammatory markers as compared to matched healthy controls is remarkably stable: the ORs were 1.46 for CRP levels >3 mg/L, 1.47 for CRP levels >1 mg/L and 1.52 for CRP levels >10 mg/L." (PMID 31258105, 2019). "However, we also found some evidence for our primary hypothesis that CRP was most increased in the subgroup of patients with treatment-resistant depression (n = 102)." (PMID 29764522, 2019). "We hypothesized that unipolar depression and bipolar depression might present with different serum levels of cytokines (IL-6 and IL-8) and CRP even in the same affective state, and that mania and depression states might also present with different serum levels of cytokines and CRP." (PMID 30762747, 2019). "Additionally, including CRP in the model did not alter the association between sleep disturbance and depression in HIV+ participants." (PMID 30249545, 2018). "Moreover, levels of CRP did not attenuate the prospective association between sleep disturbance and depression." (PMID 30249545, 2018). "Notably, other studies have reported an association of CRP with depression only in males and not in females." (PMID 29329256, 2018). "For example, elevated levels of interleukin (IL) IL-1β, IL-6, tumor necrosis factor alpha (TNFα) and C-reactive protein (CRP), and of corticotrophin releasing hormone (CRH) and cortisol, have all been described in association with antenatal symptoms of depression." (PMID 30033161, 2018). "Proinflammatory cytokines have been related to depressive disorders and studies have shown that depressed patients have high concentrations of proinflammatory cytokines (Interleukin-1, Interleukin-6, tumor necrosis factor alpha and monocyte chemoattractant protein-1) and C-reactive protein (CRP)." (PMID 29966324, 2018). "Cytokines on the other hand are more specific cell-based measures of inflammation rather than the non-specific inflammation marker CRP, and it has been shown that relevant genetic variants of specific cytokines were associated with increased risks of depression development." (PMID 29217840, 2017). "Interestingly, there is evidence that systemic inflammation falls following remission of depression, additionally Elovainio and colleagues (2009) found that the more recent the diagnosed depression or depressive episode was, the stronger the relationship between depression and high CRP." (PMID 29190710, 2017). "Similarly, the CRP rs1205 (G/A) polymorphism, and the A allele of the MCP1 gene, are both the ‘low-producing' alleles, and are both associated with an increase in the risk of depression." (PMID 27555379, 2017). "In clinical trials with individuals with major depression, they showed significant improvement in symptoms after an anti-inflammatory (infliximab) treatment and improved quality of sleep, but only in those individuals with elevated inflammation defined as elevated C-reactive protein (CRP) levels." (PMID 28923068, 2017). "Indeed, a previous study of 33 adults with a lifetime history of depression (assessed with the 9-item Patient Health Questionnaire), reported that IL6 methylation was inversely associated with circulating IL6 (and C-reactive protein), but only for individuals with lifetime depression." (PMID 29070016, 2017).
depression (continued). "Conversely depression in men is perhaps less likely to respond to weight-reducing therapies but may respond well to anti-depressant treatments that have been shown to be efficacious in individuals with high baseline CRP levels." (PMID 29190710, 2017). "Moreover, a study of an elderly population found that when controlling for age-related chronic diseases, CRP was not a statistically significant marker associated with the presence of MDD or sub-threshold depression." (PMID 27199779, 2016). "Severity of depression showed a significant negative association with the AUCg level (β=−0.086, s.e.=0.040, P=0.034), and the number of episodes showed a borderline significant association with CRP in women (β=−0.067, s.e.=0.034, P=0.050)." (PMID 26418277, 2015). "In conclusion, we have found that pre-operative depression symptoms were associated with longer post-operative hospital stays in patients undergoing CABG surgery, and that this association was mediated by changes in CRP from pre-operative to post-surgery levels." (PMID 24239712, 2014). "Also, chronic inflammation could be involved in mood disorders, as a positive relationship between depression and CRP has been reported." (PMID 24762259, 2014). "However, on multivariate analysis, depression was no longer associated with increased hs-CRP (P value = 0.187 in mild depression; P value = 0.094 in moderate depression)." (PMID 23710335, 2013). "Similarly, we found that persistently elevated levels of depression 3 months following an acute coronary syndrome event were significantly associated with elevated CRP levels, independent of several possible confounders." (PMID 23227360, 2012). "A recent analysis of the National Health & Nutrition Examination (NHANES III) survey found that patients with a history of MDD had elevated CRP levels compared to patients with no history of depression (OR = 1.64), independent of other standard CHD risk factors." (PMID 23227360, 2012). "Women are predisposed to depression with which, not BMI and CRP, but SBP is inversely associated." (PMID 22216414, 2011). "Cause–effect relationship between depression and CRP was not established." (PMID 21701640, 2011). "According to the permutation importance analysis, CRP, NLR, and albumin were identified as the most significant predictors of depression in pancreatic cancer patients across multiple ML models." (PMID 40851223, 2026). "Permutation importance analysis revealed C‐reactive protein (CRP), neutrophil‐to‐lymphocyte ratio (NLR), and albumin as key predictors of depression." (PMID 40851223, 2026). "Notably, TNF‐α antagonists like infliximab have been tested in depression: a randomized controlled trial found that while infliximab overall did not outperform placebo, it significantly improved mood symptoms in the high baseline inflammation subgroup (CRP > 5 mg/L)." (PMID 41583906, 2026). "Multiple studies have demonstrated that individuals with depression exhibit elevated proinflammatory cytokines, such as interleukin-6 (IL-6), tumor necrosis factor-α (TNF-α), and C-reactive protein (CRP), and decreased anti-inflammatory mediators." (PMID 41541965, 2025). "Meta-analytic evidence indicates elevated levels of IL-6, CRP, and TNF-α in individuals with depression." (PMID 41333345, 2025). "Cumulative studies have demonstrated peripheral proinflammatory markers, such as CRP, IL-6, IL-1β, and TNF-α, were significantly increased in individuals suffering from depression." (PMID 40108901, 2025). "Depression score and the serum concentrations of tumor necrosis factor-α (TNF-α), interleukin-6 (IL-6), and high-sensitivity C-reactive protein (hs-CRP) were assessed before and after the study." (PMID 39997208, 2025). "BMI is related to C-reactive protein, and a high level of C-reactive protein is associated with depression, confirming the assumption that other causes of peripheral inflammation (e.g., the interleukin 6 receptor [IL6R]) may affect the development of depression." (PMID 41274868, 2025).
depression (continued). "A meta-analysis of mean differences and variability in 5166 patients and 5083 controls showed that levels of CRP, IL-3, IL-12, IL-18, sIL-2R and TNF were significantly higher in patients with depression." (PMID 40141399, 2025). "Elevated C-reactive protein (CRP) and Interleukin-6 (IL-6) are consistently observed with sleep disturbance and with extreme sleep durations, and meta-analytic data in depression show increases in IL-6/ Tumor Necrosis Factor-Alpha (TNF-α) and CRP." (PMID 41662130, 2025). "Indeed, if there are some participants in the sample with undiagnosed autoimmune or inflammatory disorders that contributed to pain-type somatic symptoms, this would still represent an association between CRP and pain symptoms that is independent of anxiety or depression symptoms." (PMID 40823322, 2025). "Meta-analyzes on the connection between inflammatory mediators in depression often focus on proinflammatory cytokines such as IL-1, IL-6, TNF-α, C-reactive protein (CRP) and anti-inflammatory cytokine IL-10." (PMID 40042668, 2025). "The patients were clinically assessed based on Bath Ankylosing Spondylitis Disease Activity Index, the Total Back Pain (TBP) and Hamilton Rating Scale for Depression (HAMD) scores, erythrocyte sedimentation rate, and high-sensitivity C-reactive protein level." (PMID 40534742, 2025). "Numerous studies indicate that levels of inflammatory cytokines, including interleukin (IL)-1β, IL-6, tumor necrosis factor alpha (TNF-α), and C-reactive protein (CRP), are elevated in patients suffering from depression." (PMID 40565663, 2025). "We further collect the prevalence of DM, DR, depression, POAG and AD, gender, APOE E4 genotypes, C-reactive protein (CRP) levels to analysis." (PMID 40778276, 2025). "Class 3 is characterized by markedly elevated CRP and ESR, alongside the highest levels of anxiety, depression, and insomnia, highlighting the importance of early psychological intervention and close follow-up." (PMID 40927014, 2025). "The sample included variables of sex, age, depression symptoms (PHQ-9), anxiety symptoms (GAD-7), and inflammation marker (CRP, both original and log-transformed values) across different insomnia severity groups." (PMID 41048872, 2025). "Increased levels of interleukin-6 (IL-6), interleukin-1β (IL-1β), CCl2, C-reactive protein (CRP), and TNF-α in the blood and cerebrospinal fluid were also detected in the patients haunting by depression." (PMID 40862788, 2025). "Moreover, evidence indicates that depression may precede and augment pro-inflammatory cytokines, including interleukin-6 (IL-6) and C-reactive protein (CRP), potentially contributing to the development of cardiometabolic and other age-related diseases in healthy older adults." (PMID 41039395, 2025). "In the univariate analysis, IL-6, CRP, ESSPRI total, ESSPRI pain, and ESSPRI fatigue were statistically significant for the OR for depression." (PMID 40822847, 2025). "The anti-inflammatory effects of these beverages are thought to stem from their ability to lower levels of inflammatory markers such as C-reactive protein (CRP) and IL-6, which are often elevated in individuals with depression." (PMID 40004109, 2025). "Our study found that participants with severe depressive symptoms had significantly higher concentrations of CRP, IL-6, and TNF-α, reaffirming a robust link between inflammation and depression." (PMID 40363978, 2025). "These microbial patterns correlated with both C-reactive protein (CRP) levels and depression severity scores, which suggests their potential utility as biomarkers for MDD with comorbid AN." (PMID 40732941, 2025). "A 2023 study conducted on patients with major depressive disorder (MDD), stratified into groups with high and low CRP levels and compared with healthy controls, showed that both MDD groups exhibited significantly higher leptin concentrations than controls." (PMID 41516008, 2025).
depression (continued). "Several studies have reported elevated levels of proinflammatory cytokines, CRP and TNF-a among patients suffering from major depressive disorders." (PMID 40003621, 2025). "Both groups displayed significant decreases in HAM‐D, Beck's depression inventory (BDI), and SHAPS scores, but the combination group achieved greater improvements and significantly reduced CRP levels compared to agomelatine alone." (PMID 40129874, 2025). "The identified variables included including preoperative anxiety, preoperative depression, preoperative pain VAS, duration of use of tourniquet, pain VAS score at discharge, and C-reactive protein (CRP) one day after surgery level." (PMID 40103861, 2025). "Refining Biomarkers: Further research is needed to validate biomarkers such as CRP, IL-6, and HRV for clinical use in differentiating depression from cardiac pathology." (PMID 40218134, 2025). "In individuals with prior MI, depression increases the likelihood of recurrent myocardial infarction (MIR), which is positively correlated with elevated hs-CRP levels." (PMID 41301929, 2025). "Several cytokines including Interleukin 6 (IL6), C-reactive protein (CRP) and Tumor Necrosis Factor alpha (TNFα) have elevated levels in depression." (PMID 40352929, 2025). "Elevated inflammatory markers, such as C-reactive protein (CRP) and pro-inflammatory cytokines (e.g., IL-6 and tumor necrosis factor-alpha (TNF-α)), have been consistently observed in individuals with depression." (PMID 40303511, 2025). "Numerous studies have demonstrated that inflammatory biomarkers, such as C-reactive protein (CRP), are elevated in individuals with depression and anxiety, underscoring the role of systemic inflammation in the pathophysiology of these conditions." (PMID 40901264, 2025). "Recent research implicates inflammatory markers, particularly C-reactive protein (CRP), in insomnia, anxiety, and depression." (PMID 41048872, 2025). "CRP, C-reactive protein; GDS, Geriatric Depression Scale; IL-6, interleukin 6; IL-18, interleukin-18; MMSE, Mini Mental State Examination; NSAIDS, non-steroidal anti-inflammatory drugs." (PMID 41419753, 2025). "In adults with depression, elevated levels of IL-6 and, to a lesser extent, TNF-α and C-reactive protein (CRP) have been consistently reported." (PMID 40563330, 2025). "A complete clinical assessment, C-reactive protein (CRP) level, and depression severity assessment using the Hamilton Depression Rating Scale (HAMD-17) were performed at baseline." (PMID 40955269, 2025). "Inflammatory biomarkers such as C-reactive protein (CRP), interleukin-6 (IL-6), and tumor necrosis factor-alpha (TNF-α) are elevated in both periodontitis and depression, raising the possibility of a shared inflammatory pathway." (PMID 40656387, 2025). "Neuroinflammation has emerged as a core feature of many psychiatric disorders, particularly schizophrenia and depression, where pro-inflammatory cytokines such as IL-6, TNF-alpha, and C-reactive protein are persistently elevated." (PMID 40218925, 2025). "It has been shown that patients with major depressive disorders had increased inflammatory markers such as interleukin (IL)-1β, IL-6, tumor necrosis factor (TNF)-α and C-reactive protein (CRP)." (PMID 39394060, 2024). "This suggests that CRP may not directly increase the risk of depression." (PMID 38699297, 2024). "An increase in the inflammatory markers, like C-reactive protein (CRP), interleukin (IL)-6, and tumor necrosis factor alpha (TNF-α), is often observed in patients with depression compared with healthy individuals." (PMID 38957737, 2024). "We have thus determined the inflammatory markers CRP, AGP as well as I-FABP (marker of intestinal permeability) to better understand the interrelations between iron status, depression, and inflammation." (PMID 38265750, 2024). "Inflammatory biomarkers, including C-reactive protein (CRP), interleukins, and NLR, have been explored in relation to depression." (PMID 38756416, 2024).